STAT3 (signal transducer and activator of transcription 3)
Diseases named in the same sentence as STAT3 in open-access papers (continued):
Sharing a sentence is not in itself a finding about the gene and the disease.
tumor (continued). "In particular, STAT3 has been shown to integrate pathways which regulate tumour growth and the immune microenvironment and it is known to be deregulated in a range of adult cancer types." (PMID 22315522, 2012). "Since several studies have established the role of activated STAT3 in tumor angiogenesis, we next sought to determine the antiangiogenic potential of DIM." (PMID 22280969, 2012). "In different tumor cell lines, the up-regulation of cyclin D1 and survivin has been shown to be dependent on STAT3 activation." (PMID 22418922, 2012). "Preclinical studies using decoy antisense STAT3 oligonucleotides, dominant-negative vectors, and small-molecule inhibitors have provided convincing evidence that STAT3 is highly relevant to the growth and survival of many tumor types, in vitro and in vivo." (PMID 22488042, 2012). "Western blotting analysis of tumor lysates indicated increased apoptosis and reduced STAT3 activation." (PMID 22280969, 2012). "Immunohistochemical analysis showed that p-STAT-3 overexpression and accumulation in the tumor region, including nuclei and cytoplasm, was significantly reversed by honokiol treatment." (PMID 22937084, 2012). "In our prior studies we identified OSM as a potential driver of STAT3 phosphorylation in canine OS tumor cells and found that inhibition of STAT3 signaling disrupted OSM induced biologic activities." (PMID 23244668, 2012). "With Stat3 inhibitor, the time to tumor recurrence was significantly improved by approximately 4-fold, when compared to chemotherapy alone." (PMID 22879872, 2012). "Given that around half of ESFT samples contained activated STAT3 tumour cells, we continued to investigate the role of STAT3 in ESFT in vitro." (PMID 22315522, 2012). "The decreased tyrosine phosphorylation of STAT3 is coupled with suppression of STAT3 transcriptional activity and reduced tumor growth in vitro and in vivo." (PMID 22394684, 2012). "Consistent with the results of in vitro experiments, EP decreased U266 tumor growth as well as suppressed the expression levels of phospho-STAT3 and CD34 by immunohistochemistry." (PMID 22260501, 2012). "STAT3 relevance in oncogenesis/tumor progression is widely acknowledged, via regulating apoptosis-related genes (Bcl-XL, Mcl-1 and Survivin), proliferation- (c-myc and cyclin D1) and invasion-promoting genes (VEGF, MMP-9)." (PMID 23028842, 2012). "STAT-3 is known to exist in a high concentration in different human tumors and tumor cell lines, therefore it becomes an attractive target for cancer therapy." (PMID 22363217, 2012). "Over activation of ERK, Akt and STAT3 which are the main cell proliferation and survival factors act as promoting factors for tumor progression in NSCLC." (PMID 23133538, 2012). "Second, a reduction in STAT3 activity leads to an increased number of tumor-specific CTLs and DCs, as well as a reduced number of Treg, and thereafter an enhancement of the anti-tumor immunity." (PMID 22911830, 2012). "Together with the biochemical data, these results suggested that the ability of PTPMeg2 to inhibit the tumor growth and cell proliferation is depending on its role of regulation of phosphorylated STAT3." (PMID 22394684, 2012). "Previous work has described a high incidence of STAT3 activation in ESFT, and we were interested in confirming this finding in an independent tissue set, as well as analysing tissue distribution of activated STAT3 within the tumor microenvironment." (PMID 22315522, 2012). "Alternatively, p-STAT3 promotes tumor cells to produce multiple oncogenic cytokines, such as IL-10, which in turn activates STAT3 signaling through a positive feedback loop and inhibits functional DC stimulation." (PMID 22911830, 2012). "Accordingly, in the AOM + DSS mouse model, Becker and colleagues demonstrate that IL-6 is highly produced by CD4+ T cells and promotes tumor cell proliferation via STAT3 activation." (PMID 23109839, 2012).
tumor (continued). "It is well known that up-regulated STAT3 activity is associated with several human tumors, including AML and that STAT3 inhibition can mediate tumor regression." (PMID 23271044, 2012). "Priming of tumor cells with suboptimal concentration for short duration can significantly enhance anti-tumor activity of EGFRBi armed ATC through the inhibition of Stat3 and activation of Stat1." (PMID 23185240, 2012). "STAT3 is a well-characterized transcription factor that has been demonstrated to contribute to various processes of tumorigenesis, such as tumor cell survival and proliferation, invasion, angiogenesis and drug resistance." (PMID 22723956, 2012). "We show that Rac and STAT3 inhibition regimens are effective at blocking tumour invasion ex vivo, independently of known clinical biomarkers such as histological grade and ER status." (PMID 22689141, 2012). "Activated STAT3 can mediate oncogenic transformation in cultured cells and promote tumor formation in nude mice, thus qualifying STAT3 as a proto-oncogene." (PMID 22470194, 2012). "The 2 different mutational backgrounds of IHCA concerning gp130 and STAT3 lead to a similar morphology and immunophenotype of increased SAA/CRP in the tumor hepatocytes." (PMID 23024866, 2012). "First, the cytokines which activated the transcription factors NF-κB and STAT-3 in tumor cells also activate these same transcription factors in inflammatory cells and tumor-stromal cells, which in turn results in more inflammatory mediators being produced." (PMID 22829853, 2012). "In particular, we focused on the role of STAT3 in modulating HIFU-induced anti-tumor immune responses." (PMID 22911830, 2012). "One explanation for the putative, tumor-promoting function of IL-17A is that the expression and the function of this cytokine are closely related to the proto-oncogene Stat3." (PMID 22855687, 2012). "In summary, we have revealed a specific mechanism for M-HIFU induced anti-tumor immune response, which is mediated through inhibition of STAT3 activation in vivo." (PMID 22911830, 2012). "Increased activation of STAT-3 expression has been found in various tumor-derived cells and samples from human cancer tissues." (PMID 22937084, 2012). "AZD1480 demonstrated a reduction in microvascular density, likely secondary to STAT3 inhibition in the tumor vascular endothelium." (PMID 23013619, 2012). "This property implicates an inhibitory effect of F4.3.7 on tumour progression which was also reflected by the downregulation of the Jun family of oncogenes and the suppression of Stat3 activity." (PMID 22474515, 2012). "To confirm the inhibitory role of PTPMeg2 on tumor growth is depended on regulation of STAT3 phosphorylation, we used v-Src transformed NIH3T3 fibroblasts in a xenograft tumor model." (PMID 22394684, 2012). "For example, the broad acting kinase inhibitor sunitinib has recently been shown to elicit anti-tumor activity by STAT3 inhibition." (PMID 22899991, 2012). "This is also in agreement with other reports addressing that inhibitory effect of STAT3 level on cucurbitacin E and triterpene-derived natural products treated human tumor cells and umbilical vascular endothelial cells in vitro." (PMID 22272214, 2012). "STAT3 is abnormally activated and is related to tumor stage and prognosis in gastrointestinal tumors." (PMID 23170117, 2012). "Immunohistochemical staining of representative tumor sections showed significant phospho-STAT3 downregulation by AZD1480 in tumor cells and stromal cells (endothelial cells)." (PMID 23056499, 2012). "STAT3 is also involved in tumor progression through inducing angiogenic factors, such as vascular endothelial growth factor (VEGF)." (PMID 23118721, 2012). "There is accumulating evidence that STAT3 is an important facilitator of tumor angiogenesis and its activation correlates with VEGF production in a variety of human cancers." (PMID 22530037, 2012).
tumor (continued). "Further, in ongoing screen of lentivirally expressed shRNAs (pGIPZ-shRNAmir library, Open Biosystems) to disrupt function of candidate regulators of tumor-initiating cells, we identified shRNAs targeting Stat3 decreased mammosphere formation efficacy (MSFE)." (PMID 22879872, 2012). "The Signal Transducer and Activator of Transcription 3 (STAT3) is activated in tumor cells, and STAT3-inhibitors are able to induce the death of those cells." (PMID 22423663, 2012). "Inhibiting STAT3 in either tumor cells or tumor-infiltrating myeloid cells elicits Th1 anti-tumor immune responses, concomitant with an increased number of CTLs and decreased Tregs." (PMID 22911830, 2012). "Phospho-STAT3 (Y705), the activated form of STAT3, plays a key role in eliciting immune surveillance, tumor development and tumor metastasis." (PMID 22911830, 2012). "The staining for HER2 and phosphorylated STAT3 were reduced; whereas cleavage of caspase 3 was increased in the tumor sections from PEITC-treated mice." (PMID 22824293, 2012). "Previous studies on embryonic development and tumor cells support our findings of cross-talk between Wnt/β-catenin and STAT3 pathways." (PMID 23056515, 2012). "STAT3 is a latent transcription factor found in the cytoplasm that plays an important role in tumor growth and survival." (PMID 23251519, 2012). "Aberrant STAT3 activity plays a central role in dysregulated growth and survival of tumor cells as well as in promoting angiogenesis." (PMID 22911830, 2012). "STAT3 activation can resist apoptotic machinery relied anti-tumor therapies, and also enhance the growth of tumor cell." (PMID 22303479, 2012). "Stat3 is known to have tumor-promoting properties as its expression in tumor cells has been associated with enhanced tumor cell survival, proliferation, and angiogenesis as well as with an accumulation of Tregs and myeloid-derived suppressor cells." (PMID 22855687, 2012). "In this study, our results from RT-PCR clearly demonstrated that the down-regulation of p-STAT3 was accompanied by the decreased expression of cyclin D1 and Bcl-xL in tumor tissue following M-HIFU treatment." (PMID 22911830, 2012). "Resulting tumor-bearing mice were then randomized into the four arms, namely vehicle, docetaxel (20mg/kg), Stat3 inhibitor (C188) (12.5 mg/kg), and the inhibitor+docetaxel combination." (PMID 22879872, 2012). "STAT3 regulates basic biologic processes important in tumorigenesis including cell cycle progression, survival, tumor angiogenesis, and tumor-cell evasion of the immune system." (PMID 23166634, 2012). "In contrast, WP1066 has been shown to specifically prevent STAT3 phosphorylation at low doses in tumor models up to 3 weeks after the last injection of the inhibitor." (PMID 22418922, 2012). "Detailed insights into the role of STAT3 in tumor development, progression and drug resistance directly point to new specific targeting strategies for tumor therapy." (PMID 23554768, 2012). "FACS analysis (Procedures S1) of BCM2665 tumor cells (∼10,000 cells) demonstrated that the Stat3 inhibitor C188 reduced ALDH1 levels in treated samples." (PMID 22879872, 2012). "Our results also show that targeting STAT3 potentiates the effect of cisplatin both in culture as well as in a tumor xenograft model." (PMID 22280969, 2012). "Although in this study we focused on the mechanism associated with STAT3, involvement of other mechanisms for M-HIFU induced anti-tumor immunity is also possible, and will be investigated in the future." (PMID 22911830, 2012). "Analysis of mechanisms underlying this effect revealed that IL-21 sustains CD4+ T cell infiltration in the tumor and peritumor areas and enhances the production of IL-6 and IL-17A as well as STAT3 activation." (PMID 23109839, 2012).
tumor (continued). "These in vivo results are consistent with our in vitro results showing a potent induced effect of fucoxanthin on the apoptosis of tumor, which is associated with EGFR/STAT3 signal pathway." (PMID 23118721, 2012). "STAT3 inhibitors have been shown to reduce tumor microvessel density in tumors but a direct anti-angiogenic activity has not been described." (PMID 22530037, 2012). "We examined RM-9 tumors harvested at three different time points (10-, 15-, and 20-days) post inoculation for p-STAT3 using IHC and the results indicate constitutive STAT3 activation in RM-9 tumors over the 20 days of tumor development." (PMID 22911830, 2012). "Together, these data demonstrate that FLLL32 exhibits improved efficacy at abrogating STAT3 functional activity and its effects in enhancing tumor cell survival in many cancer cell lines as compared to curcumin and other STAT3 inhibitors." (PMID 21443800, 2011). "As this pro-oncogenic transcription factor is constitutively activated in many types of cancer, it is highly likely that STAT3 also plays an important role in cell proliferation, cell survival and tumor transformation." (PMID 21738692, 2011). "Expression of collagen IV protein surrounding the tumor cells was complete and continuous in tumors of STAT3-silenced SW1990 cells, whereas collagen IV expression was incomplete and discontinuous within control tumors." (PMID 21991388, 2011). "Expectedly, the disruption of STAT-3 signaling, for example, using dominant negative STAT-3 variants in the mouse, leads to tumor regression or growth control in vivo." (PMID 22110524, 2011). "The Janus kinase (JAK)/STAT3 signaling plays an important role in the regulation of cell growth and differentiation and tumor invasion and metastasis in diverse human cancers." (PMID 21991388, 2011). "Constitutive STAT3 activation is frequently involved in uncontrolled tumor cell proliferation and therefore constitutes a valuable target for anti-tumor therapy." (PMID 21486470, 2011). "Previous studies have shown that STAT3 inhibitors can suppress tumor cell growth in vivo and tumor growth in a tumor xenograft mouse model." (PMID 22136659, 2011). "Data from the current study clearly indicate that STAT3 does play a crucial role in the regulation of tumor growth, invasion, and angiogenesis." (PMID 21991388, 2011). "Growth rate of the STAT3-silenced tumor cells in nude mice was significantly reduced compared to in the control vector tumors and parental cells-generated tumors." (PMID 21991388, 2011). "We also found that expression of collagen IV protein surrounding the tumor cells in control tumors was incomplete and discontinuous, whereas it was complete and continuous in tumors of STAT3-silenced SW1990 cells following immunohistochemical staining." (PMID 21991388, 2011). "The differential effects of STAT3 blockade based on tumor genetics highlights the importance of developing molecular classification schemes that reflect responsiveness to various immunotherapy approaches." (PMID 22190972, 2011). "In SW 480 cells, both NF-κB and STAT3 are activated, suggesting a constitutive interleukin secretory loop, as described for several tumor cell systems (see:)." (PMID 21486470, 2011). "In vivo experiments were conducted with mice given diethylinitrosamine (DEN), which induces HCC was used to investigate the role of STAT3 expression in monocytes on tumor growth." (PMID 22136659, 2011). "Since STAT3 plays a critical role in tumor initiation and progression, inhibition of STAT3 activation would be an effective approach for cancer prevention and treatment." (PMID 21806788, 2011). "An IL-6 neutralizing mAb reduced STAT3 activation and also completely reversed IL-17-stimulated tumor invasion in vitro, while exogenous IL-6 completely recovered IL-17-induced invasion of siRNA-AKT-SMMC7721 and siRNA-AKT-Huh7 cells." (PMID 22171994, 2011).
tumor (continued). "AKT-dependent IL-6/STAT3 activation was therefore suggested to be responsible for the tumor promoting effects of IL-17 on HCC." (PMID 22171994, 2011). "Tumor plane exhibited a positive trend with expression of STAT3 and pSTAT3, which were expressed in 51.16% and 18.6% of subcuitis, followed by the muscular plane (78.3% and 47.8%)) and body cavity (87.5% and 56.3%)." (PMID 21575192, 2011). "For example, Wnt5a can mediate migration via PKC activation, by inducing an epithelial to mesenchymal transition (EMT), by inhibiting metastasis suppressors such as matrix metalloproteases and by regulating expression of tumor antigens via STAT3." (PMID 21494614, 2011). "FLLL32 possesses superior biochemical properties and more specifically targets STAT3, a transcription factor important in tumor cell survival, proliferation, metastasis, and chemotherapy resistance." (PMID 21443800, 2011). "Malignant tumors were 107.3 times more likely to express STAT3, when benign or intermediate tumor is the reference (OR = 107.3, 95% CI: 20.24-569)." (PMID 21575192, 2011). "MiR-34a expression negatively affects CD133+/CD15+ tumor-propagating cells, then we assay through reverse-phase proteomic arrays, Akt and Stat3 signaling hypo-phosphorylation." (PMID 21931765, 2011). "In the mouse tumor models, cells pretreated with Src and STAT3 siRNA by transfection or treated by direct injection of siRNA into the tumor showed a strong reduction in the ability to form primary tumors." (PMID 21541295, 2011). "Further investigations will be necessary to ascertain how to optimize the STAT3 inhibitors in combination with other immune therapeutics in the setting of hypoxic tumor microenvironments." (PMID 21283755, 2011). "Several transcriptional targets of STAT3 are important contributors to tumor biology and activation of STAT3 by gp130-mediated mechanisms is known to be oncogenic." (PMID 21481226, 2011). "The other 3 groups, including mice changed from control to Src+STAT3 siRNA, the Src+STAT3 group, and the Src+STAT3+Myc group had smaller average tumor sizes of 892, 878, and 610 mm3, respectively." (PMID 21541295, 2011). "We and others have shown that constitutive activation of STAT3 provides cancer cells with growth and survival advantages and enhances tumor angiogenesis and metastasis." (PMID 22046235, 2011). "In the case of HT-29 cells, where dominant negative Stat3 expression appears to completely block Stat3 activity, the tumor size is reduced even though host supplied growth factors are present." (PMID 21595927, 2011). "TAMs become polarized toward immunosuppressive and tumor supportive phenotypes (M2) via the STAT3 pathway and then contribute to angiogenesis and tumor invasion." (PMID 21283755, 2011). "In vivo experiments show that intravenous injections of MSCs loaded with Adv-Stat3(-) can preferentially home to the tumor site, and the number of homing cells increases gradually with time." (PMID 22054049, 2011). "Tumor invasion into the vessel and muscle were also suppressed in the STAT3-silenced tumors compared to controls." (PMID 21991388, 2011). "The expression levels of STAT3 and pSTAT3 were analyzed by immunoblotting in representative soft tissue tumor samples." (PMID 21575192, 2011). "We also show that there is a possible role for Stat3 at the cell membrane that contributes to the malignant phenotype of invading tumor cells." (PMID 21595927, 2011). "The overexpression of STAT3 and pSTAT3 (Tyr705) has been observed in human soft tissue tumor samples and the expression level increases with tumor grade progression." (PMID 21575192, 2011). "A considerable number of Adv-Stat3(-)-loaded MSCs were found in the lungs, liver, spleen, and tumor periphery at 24 hours." (PMID 22054049, 2011). "In the previous study tumor expression of STAT3 was correlated with disease progression and poor survival rates." (PMID 22136659, 2011).